KCNT1 (potassium sodium-activated channel subfamily T member 1)
Diseases named in the same sentence as KCNT1 in open-access papers (continued):
Sharing a sentence is not in itself a finding about the gene and the disease.
epilepsy (continued). "Quinidine has been proposed as a therapy for patients with KCNT1 epilepsy because of the effectiveness of high doses for correction of GOF mutations in vitro." (PMID 37901435, 2023). "Here, we showed that reduction of Kcnt1 expression is protective in mouse models of Scn1a and Scn8a epilepsy." (PMID 37901435, 2023). "Conventional antiseizure medications have limited efficacy in the treatment of KCNT1-related epilepsies, which further reduces patients’ quality of life." (PMID 38003469, 2023). "In a large cohort of patients with KCNT1-related epilepsy, 20% of subjects receiving QND treatment showed a >50% reduction in seizure frequency, with sustained seizure freedom occurring only in one patient." (PMID 36297665, 2022). "The preclinical evidence presented here provides proof of concept for ASO-based gene silencing as a therapeutic approach in KCNT1 gain-of-function epilepsies." (PMID 36173683, 2022). "In these disorders and epilepsies, carriers of whole-gene deletions are less severely affected than carriers of single point mutations (e. g., in SCN2A, KCNT1, KCNA2, SPTAN1)." (PMID 38835873, 2022). "A subsequent study of patients with KCNT1-related epilepsy noted a > 50% seizure reduction in 20% of patients, and with only a few achieving transient seizure freedom." (PMID 35250833, 2022). "The efficacy of quinidine on KCNT1-related epilepsy has been examined in many studies but remains controversial." (PMID 35116000, 2021). "Data were collected from 30 patients treated for KCNT1-related epilepsy at our hospital [17 boys and 13 girls; age at onset, 1.25 (0.04–36) months]." (PMID 35116000, 2021). "Less is known about other genetic encephalopathies, such as the KCNT1-related epilepsy of infancy with migrating focal seizures." (PMID 33827647, 2021). "In this study, the overall ER for KDT for KCNT1-related epilepsy was 43.5–44.4%, which was much higher than that for quinidine and ASMs." (PMID 35116000, 2021). "For genes associated with neonatal and infantile epilepsies, including KCNQ2, KCNT1, PRRT2, and SCN8A, we found that EMR usage was concentrated in the first year of life." (PMID 34031551, 2021). "We collected the data for KCNT1-related epilepsy cases from our hospital's medical records and the literature." (PMID 35116000, 2021). "In this study, KDT seems to have a significantly higher efficacy for KCNT1-related epilepsy than did ASMs and quinidine." (PMID 35116000, 2021). "Further, we explored the efficacy-genotype correlations of KCNT1-related epilepsy based on data of our patients and patients reported in the literature." (PMID 35116000, 2021). "Clarifying the relationship between genotype and curative effect will help optimize treatments and improve outcomes in KCNT1-related epilepsy in clinical practice." (PMID 35116000, 2021). "The discrepancy between abnormal behavior seen in Kcnt1−/− mice and epilepsy seen in Kcnt1+/R455H mice suggests that these two phenotypes involve different pathways." (PMID 32081855, 2020). "KCNT1 is linked to severe forms of ADSHE and other epilepsies, particularly epilepsy of infancy with migrating focal seizures, accompanied by neurological and psychiatric comorbidities." (PMID 33255633, 2020). "The present work demonstrating that Kcnt1+/R455H knock-in mice phenocopy many aspects of the human epilepsy provides an animal model for the development of new therapies for these devastating diseases." (PMID 32081855, 2020). "Such an approach has been attempted in KCNT1-related epilepsy, which is especially refractory to common AEDs." (PMID 33255633, 2020).
epilepsy (continued). "We identified a cohort of 31 patients with epilepsy of infancy with migrating focal seizures (EIMFS) and screened for variants in KCNT1 using direct Sanger sequencing, a multiple-gene next-generation sequencing panel, and whole-exome sequencing." (PMID 29196579, 2018). "Recently, quinidine has been identified as a novel therapy for patients with KCNT1-related epilepsy." (PMID 29196579, 2018). "A second case with KCNT1-related epilepsy, showing a novel phenotype with developmental regression and severe nocturnal focal and secondarily generalised seizures starting in early childhood, did not respond to treatment with quinidine." (PMID 28082152, 2018). "Evaluation of new therapies, including KCNT1-specific blockers, remains a research priority for this devastating pharmacoresistant group of epilepsies." (PMID 29196579, 2018). "We undertook detailed clinical, molecular genetic, and functional characterization of a cohort of patients with KCNT1-related epilepsy." (PMID 29196579, 2018). "This study identified a known drug, antrafenine, that reduces KCNT1 channel activity, reduces seizure activity in Drosophila, and crosses the blood–brain barrier in the mouse, suggesting its potential applicability as a new treatment for KCNT1 epilepsy." (PMID 40944494, 2025). "In the same way, several DEEs caused by mutations in CDKL5, DNM1, KCNT1, SCN1A, SCN2A, SCN8A, and UBA5 genes, which present severe pharmaco-resistant epilepsy, are increasingly becoming targets for RNA molecules that aim to restore neuronal excitability and network function." (PMID 41244709, 2025). "The seizure phenotypes in the Drosophila models were affected by the addition of drugs currently used to treat people with KCNT1 epilepsy, suggesting they may be useful as preclinical tools for screening new therapeutics for these epilepsies." (PMID 38336906, 2024). "Finally, animal models of KCNT1-related epilepsies are necessary to preclinically validate identified lead compounds and to clearly link their potential anti-epileptic effects to the sole KCNT1 modulation." (PMID 38931004, 2024). "Our successful demonstration that viral expression of Slack’s C-terminus prevents epilepsy-related SlackG269S-induced seizures in mice warrants further translational evaluation for developing therapeutic interventions to treat KCNT1-related epilepsy." (PMID 38289338, 2024). "However, our discovery of the Slack-NaV1.6 complex challenges the traditional view that Slack acts as an isolated target in KCNT1-related epilepsy." (PMID 38289338, 2024). "Selectivity assays over HEK293 cells expressing many different ion channels (KCNT2, Slo, GIRK1/2, Kv2.1, TREK1, hERG, NaV1.7, and Cav3.2) were performed, along with the evaluation of the activity of the initial hit selection over the epilepsy-related KCNT1 mutants G288S and R428Q." (PMID 38931004, 2024). "While it is not known if any humans have full loss of KCNT1 expression, point mutations of the channel in humans give rise to multiple early-onset epilepsies associated with very severe intellectual disability." (PMID 39595574, 2024). "The results support the hypothesis that ASO-mediated KCNT1 reduction could be therapeutically useful in the treatment of KCNT1 epilepsies." (PMID 39595574, 2024). "Having shown that expression of G228S, R398Q and R928C mutant KCNT1 in GABAergic neurons gives a seizure phenotype, we next investigated if the phenotype generated by each of the three mutations responded to some of the drugs most commonly used to reduce seizures in patients with KCNT1-epilepsy." (PMID 38336906, 2024). "In this study we sought to investigate if Drosophila could be used to model KCNT1-epilepsy and if the seizure phenotype responded to some of the drugs currently used to treat patients." (PMID 38336906, 2024). "Further studies are needed to verify whether this approach could be also applied to other phenotypes of the KCNT1-related epilepsies spectrum." (PMID 38644974, 2024).
epilepsy (continued). "KCNT1 encodes the sodium-activated potassium channel known as SLACK, making small molecule inhibitors of SLACK channels a compelling approach to the treatment of EIMFS and other epilepsies associated with KCNT1 mutations." (PMID 39683653, 2024). "Epilepsy of infancy with migrating focal seizures (EIMFS) is a rare, serious, and pharmacoresistant epileptic disorder often linked to gain-of-function mutations in the KCNT1 gene." (PMID 39683653, 2024). "In vivo, quinidine has mixed efficacy in KCNT1 epilepsy patients." (PMID 37901435, 2023). "Clinical application of quinidine in KCNT1 epilepsy has mixed success." (PMID 37901435, 2023). "Other studies indicate that quinidine could be a candidate drug for the treatment of KCNT1-positive epilepsies even though its efficacy has been demonstrated in only a small number of patients." (PMID 37630977, 2023). "In three patients with sleep-related hypermotor epilepsy phenotype and KCNT1 mutation, epilepsy surgery did not achieve seizure freedom, although epilepsy severity improved in one (Engel class II)." (PMID 35492509, 2022). "This corresponds well with the data obtained from mouse models of KCNT1-mediated epilepsy." (PMID 36499459, 2022). "This study compared the efficacy of ASMs, quinidine, and KDT on KCNT1-related epilepsy treatment." (PMID 35116000, 2021). "However, these diseases are generally highly resistant to traditional anti-seizure medications (ASMs), and the optimal treatment strategy for KCNT1-related epilepsy has yet to be determined." (PMID 35116000, 2021). "The ketogenic diet is a high-fat, low-carbohydrate diet; according to previous reports, it controls seizures by regulating glycolysis, mitochondrial metabolism, neuronal transmission, polyunsaturated fatty acid levels, and other cellular mechanisms and effectively treats KCNT1-related epilepsy." (PMID 35116000, 2021). "One of the most severe NDD + E, epilepsy of infancy with migrating focal seizures (EIMFS), is associated with de novo GoF mutations in KCNT1, encoding the sodium‐activated potassium channel subunit KCa4.1." (PMID 32880951, 2021). "To test this hypothesis, we compared the efficacy of these treatments by retrospectively analyzing the outcomes of patients with KCNT1-related epilepsy at our institution and in the literature." (PMID 35116000, 2021). "We evaluated the efficacy of ASMs, KDT, and quinidine for treating KCNT1-related epilepsy." (PMID 35116000, 2021). "Finally, we compared the clinical efficacy of quinidine and KDT for treating KCNT1-related epilepsy." (PMID 35116000, 2021). "Efficacy of quinidine and ketogenic diet in the treatment of KCNT1-related epilepsy." (PMID 35116000, 2021). "Therefore, in this study, we evaluated the efficacy of ASMs, quinidine, and KDT in KCNT1-related epilepsy." (PMID 35116000, 2021). "Additional patients with non-EIMFS early-onset epilepsy in whom we identified KCNT1 variants on local diagnostic multiple gene panel testing were also included." (PMID 29196579, 2018). "Based on the in vitro analysis and their inhibition of KCNT1 channels, the 4 drugs antrafenine, atorvastatin, nelfinavir mesylate, and regorafenib, were selected to be analyzed in vivo for their effects on the seizure phenotype in 3 humanized Drosophila models of KCNT1 epilepsy." (PMID 40944494, 2025). "However, this may be explained by accumulating evidence that overactivity of mutant KCNT1 channels in inhibitory neurons contributes to pathogenicity in KCNT1 epilepsy." (PMID 40944494, 2025). "To ascertain whether our KCNT1 Drosophila models may be useful as tools for assessing drug treatments for KCNT1-epilepsy, we looked at the effects on the seizure phenotype for some of the drugs currently used to treat patients and reduce seizures in some patients." (PMID 38336906, 2024).
epilepsy (continued). "Gain-of-function mutations in the KCNT1 gene, which encodes the sodium-activated potassium channel known as SLACK, are associated with the rare but devastating developmental and epileptic encephalopathy known as epilepsy of infancy with migrating focal seizures (EIMFS)." (PMID 38893312, 2024). "Variants in KCNT1 are associated with a wide spectrum of epileptic phenotypes, including epilepsy of infancy with migrating focal seizures (EIMFS), non-EIMFS developmental and epileptic encephalopathies, autosomal dominant or sporadic sleep-related hypermotor epilepsy, and focal epilepsy." (PMID 38644974, 2024). "However, it has shown variable results and serious side effects in some KCNT1 epilepsy patients." (PMID 38336906, 2024). "Further investigation may identify other types of epilepsy that respond to reduction of KCNT1." (PMID 37901435, 2023). "Some early gene-based “precision therapies,” such as quinidine for KCNT1-associated epilepsy with migrating seizures in infancy, have now failed to confirm high expectations in larger patient groups, and common antiseizure medications have been shown to be superior to precision therapy approaches." (PMID 38835873, 2022). "The reason for such a discrepancy is not clear, however, this may indicate that different KCNT1 GoF mutations cause epilepsy by different mechanisms." (PMID 36499459, 2022). "To date, there is no effective therapy to treat KCNT1-associated epilepsies." (PMID 36173683, 2022). "Therefore, we hypothesized that KDT would better control KCNT1-related epilepsy than do ASMs and quinidine." (PMID 35116000, 2021). "KDT may be better at treating KCNT1-related epilepsy than quinidine; ASMs were the least effective." (PMID 35116000, 2021). "Hence, KDT potentially has a higher ER for KCNT1-related epilepsy." (PMID 35116000, 2021). "KCNT1 had not previously been implicated in OS and would not therefore have been tested for this specific phenotype, even though it was described for other severe epilepsy phenotypes after we started this project." (PMID 24463883, 2014). "The genetic underpinnings of epilepsy have helped in the classification of these syndromes, and examples now include rare monogenic forms involving KCNA2, KCNT1, and SCN1A." (PMID 40871704, 2025). "Although these findings provide a strong mechanistic basis for understanding how KCNT1 GOF disrupts neuronal physiology and network behavior to lead to seizure disorders, key issues remain unresolved." (PMID 39392867, 2024). "We have shown a gene-specific and dose-dependent knockdown of Kcnt1 mRNA achieved with the Kcnt1 ASO in L/L mice which significantly improved survival, epilepsy, and behavioral comorbidities and complete rescue of mating." (PMID 36173683, 2022). "Studies focused solely on epilepsy without reporting cognitive or intellectual outcomes were excluded, as this review specifically addressed the role of KCNT1/Slo2 channels in cognitive impairment." (PMID 41189825, 2025). "There are currently no effective treatments for KCNT1 epilepsies, but suppressing overactive channels poses a potential strategy." (PMID 40944494, 2025). "There are currently no highly effective treatments for KCNT1-epilepsy and no drugs available that specifically target the KCNT1 channel." (PMID 38336906, 2024). "Ingestion of medicinal cannabis derivatives containing the compound cannabidiol (CBD) reduces the frequency of seizures in some KCNT1-epilepsy patients and has not been reported to exacerbate seizures." (PMID 38336906, 2024). "More specific KCNT1 channel blockers may be more effective for treatment of KCNT1, SCN8A, and SCN1A epilepsy." (PMID 37901435, 2023). "Our results implicate KCNT1 as a therapeutic target for treatment of SCN1A and SCN8A epilepsy." (PMID 37901435, 2023).
epilepsy (continued). "Due to its ability to inhibit the sodium-activated potassium channel encoded by a potassium sodium-activated channel subfamily T member 1 (KCNT1) gene, QND has been used in epilepsy of infancy with migrating focal seizures (EIMFS) (#608167) caused by KCNT1 genetic variants." (PMID 36297665, 2022). "A single ICV injection of a Kcnt1 gapmer (i.e., short DNA strands flanked by strands of RNA mimics) ASO in a mouse model of KCNT1-epilepsy led to significant reduction in seizure frequency and increased overall survival compared to mice treated with a control (i.e., non-hybridizing) sequence." (PMID 35250833, 2022). "In this study, the overall ER for quinidine for KCNT1-related epilepsy was ~26.0–30.0%, indicating that not all patients with seizures benefit from quinidine treatment." (PMID 35116000, 2021). "Expression of each mutant channel in GABAergic neurons gave a seizure phenotype which responded either positively or negatively to 5 frontline epilepsy drugs most commonly administered to patients with KCNT1-epilepsy, often with little or no improvement of seizures." (PMID 38336906, 2024). "In addition, targeting Kcnt1 transcript in Scn8a mutant mice doubled their lifespan and extended the survival of Scn1a mutant mice, suggesting KCNT1 could be a therapeutic target for the treatment of SCN1A and SCN8A epilepsy." (PMID 39513870, 2024). "Similarly, an observational study of 43 patients to evaluate the treatment responsiveness of patients with KCNT1-related epilepsy reported that quinidine was not utilized in any patients with an ADNFLE phenotype, whereas quinidine treatment was attempted in 17 patients with an EIMFS phenotype." (PMID 37630977, 2023).
epileptic encephalopathies (17 papers, 2014 to 2025). "Another surprising finding was the asymptomatic heterozygous mother of a child with epileptic encephalopathy and intractable seizures secondary to the previously reported pathogenic variant in KCNT1 NM_020822.3:c.862G>A; p.(Gly288Ser)." (PMID 39669259, 2023). "Mutations in the Potassium channel subfamily T member 1 (KCNT1) gene have been reported in a range of epileptic encephalopathies." (PMID 30804880, 2019). "Screening of 362 patients with early-onset epileptic encephalopathies showed nine heterozygous KCNT1 mutations, predominantly de novo, clustered in the regulator of conductance for potassium (RCK) domain and transmembrane segment 5, with several recurrent variants." (PMID 41189825, 2025). "Among these 11 patients, 3 patients relapsed from not taking the medication irregularly, 2 patients harbored gene mutations (CDKL5 and KCNT1) associated with epileptic encephalopathy, and the remaining 6 patients had abnormal findings on brain MRI (e.g., encephalomalacia and pachygyria)." (PMID 37217894, 2023). "KCNT1 is associated with epilepsy of infancy with migrating focal seizures, autosomal dominant nocturnal frontal lobe epilepsy, and other types of early onset epileptic encephalopathies." (PMID 30185235, 2018). "Here, we report the application of Therapeutic Drug Monitoring (TDM) in pediatric patients carrying KCNT1 genetic variants and orally treated with QND for developmental and epileptic encephalopathies (DEE)." (PMID 36297665, 2022). "For example, we found a KCNT1 mutation in a child later recognised to have classical EIMFS (case 23) rather than the initial diagnosis of epileptic encephalopathy with multifocal EEG discharges." (PMID 26993267, 2016). "Using a targeted resequencing approach, we screened KCNT1, PIGQ, CBL and CSNK1G1 in a large cohort of epileptic encephalopathy cases from Australia." (PMID 24463883, 2014).